ASCL4 (achaete-scute family bHLH transcription factor 4)
Description:
Could be a transcriptional regulator involved in skin development.
Synonyms: ASH-4; hASH4; bHLHa44
Tractability: No criterion of Open Targets' tractability assessment is met for any kind of drug.
Gene: Protein-coding gene on chromosome 12 (107,774,704 to 107,776,644, forward strand). Ensembl gene ENSG00000187855.
Subcellular location: Nucleus
Gene Ontology:
Molecular function: protein binding; DNA-binding transcription factor activity, RNA polymerase II-specific; RNA polymerase II transcription regulatory region sequence-specific DNA binding; DNA-binding transcription repressor activity, RNA polymerase II-specific; protein dimerization activity
Biological process: regulation of transcription by RNA polymerase II; skin development; animal organ development; epithelium development; negative regulation of transcription by RNA polymerase II
Cellular component: chromatin; RNA polymerase II transcription regulator complex; nucleus; transcription regulator complex
Genetic constraint (gnomAD): Loss-of-function variants: 1 observed, 0.62 expected, observed/expected ratio (o/e) 1.6, 90% interval 0.32 to 1.92. That is too few expected variants to judge how well the gene tolerates losing a copy. Missense variants: 330 observed, 217.53 expected, observed/expected ratio (o/e) 1.52, 90% interval 1.39 to 1.66. Synonymous variants: 137 observed, 97.15 expected, observed/expected ratio (o/e) 1.41, 90% interval 1.23 to 1.62.
Homologues: Orthologues: chimpanzee ASCL4 (97% identical), macaque ASCL4 (90% identical), pig ASCL4 (79% identical), dog ASCL4 (70% identical), mouse Ascl4 (60% identical), rat Ascl4 (58% identical), tropical clawed frog ascl3 (41% identical), Drosophila melanogaster ase (26% identical), Drosophila melanogaster ac (20% identical). Paralogues in human: ASCL5 (38% identical), ASCL3 (33% identical), ASCL1 (31% identical), ASCL2 (28% identical).
Diseases named in the same sentence as ASCL4 in open-access papers:
ASCL4 is named in the same sentence as 15 diseases in open-access papers, as found by Europe PMC text mining. Sharing a sentence is not in itself a finding about the gene and the disease. The quoted sentences say what the papers report.
glioma (3 papers, 2022 to 2023). A benign or malignant brain and spinal cord tumor that arises from glial cells (astrocytes, oligodendrocytes, ependymal cells). "There were 5 ferroptosis-associated genes (KEAP1, NFE2L2, NOX4, ATF4, ASCL4) that have been tested in human glioma with different research methods." (PMID 36627482, 2023). "Furthermore, RT-qPCR and Western blot analysis revealed that the enhanced transfection with HOXD10 siRNAs resulted in a decrease in both ASCL4 mRNA and protein expression in glioma cells." (PMID 38138552, 2023). "ASCL4 was considered as a sensitive monitor as well as an important contributor of ferroptosis and eliminated the inhibition of GPX4 on ferroptosis in osteosarcoma cells, and overexpression of ACSL4 in glioma significantly reduced GPX4 level and contributes to ferroptosis." (PMID 36407113, 2022).
Stroke (2 papers, 2021 to 2022). Sudden impairment of blood flow to a part of the brain due to occlusion or rupture of an artery to the brain. "Recent studies have shown that ASCL4-mediated ferroptosis is involved in the pathogenesis of acute brain injuries, including stroke and traumatic brain injury." (PMID 35855863, 2022).
Arthritis (1 paper, 2024). Inflammation of a joint. "Therefore, the Mg-induced reduced expression of Ascl4 may reduce ferroptosis and contribute to a protective effect in arthritis." (PMID 39683640, 2024).
blood disease (1 paper, 2021). A disease that occurs in the blood. "The top candidates include TNFAIP3, which has been reported before, but also include other, novel regions, containing genes involved in blood diseases (CYCS), neurological diseases (PRKCH, KCNH5, LRNN1), metabolism (SFRP4, SUMF1), and skin development (ASCL4, RAB27A)." (PMID 34032215, 2021).
breast carcinoma (1 paper, 2015). "The possibility of using an ASCL4 inhibitor together with rapamycin may provide a useful combinatory therapy to target new types of cancer, including breast cancer." (PMID 26536660, 2015).
colon tumor (1 paper, 2021). "We found that the expression levels of some genes enriched in IL-11+ fibroblasts, including Wnt5a, Mmp13, Timp1, Il1rl1, Cxcl5, Saa3, Inhiba, Ascl4, and Tnfrsf11b, were elevated in mouse AOM/DSS-induced colon tumor tissues." (PMID 33863879, 2021).
tumor (8 papers, 2022 to 2025). "ASCL4 protein levels were significantly higher in C/C vs. C/HF mice and in tumours, compared to normal tissues in all other diet groups." (PMID 39203941, 2024). "Research has found that the expression of ASCL4 in tumor cells is regulated by multiple mechanisms." (PMID 40050614, 2025). "By immunohistochemistry, a significant increase of ASCL4 and ALDH1A3 expression and a significant decrease of GPX4 expression was observed when comparing primary and corresponding recurrent tumor." (PMID 35530303, 2022). "In addition, IFN-γ secreted by CD8+ T cells stimulates ASCL4 expression in tumor cells through IRF1, which leads to the upregulation of ferroptosis in tumor cells, improving the immune checkpoint blockade (ICB)-induced antitumor immunity." (PMID 41373022, 2025). "It is necessary to explore whether NEDD4L could suppress tumor progression via targeting other ferroptosis core genes, such as GPX4, ASCL4 and FTH1." (PMID 39557844, 2024). "mRNA levels of Ascl4 were not significantly different between groups, although there was a pattern of increased expression in tumours from C/C and HF/C animals, while levels of Cpt1a, Acad11 and Srebp1c were all significantly decreased in C/C and HF/C tumours relative to non-tumour tissues." (PMID 39203941, 2024). "Finally, to confirm if protein levels of genes that were differentially expressed between mouse diet groups and/or tumours were similarly altered, Western blots of mouse non-tumour and tumour tissues were analysed for expression of G6PD, ASCL4 and SREBP1." (PMID 39203941, 2024).
cancer (2 papers, 2015 to 2023). A tumor composed of atypical neoplastic, often pleomorphic cells that invade other tissues. "Owing to the heterogeneity of tumors, the role of ASCL4 in different cancers is not consistent, and the mechanism of ACSL4 in cancer promotion and inhibition is complex and variable." (PMID 37056351, 2023).
ASCL4 also shares sentences with these, for which no sentence is quoted: brain injury (1 paper); COVID-19 (1); esophageal cancer (1); gastric cancer (1); neurological diseases (1); Obesity (1); osteosarcoma (1).